FOXN1 (forkhead box N1)
Diseases named in the same sentence as FOXN1 in open-access papers (continued):
Sharing a sentence is not in itself a finding about the gene and the disease.
hypotrichosis (1 paper, 2015). A congenital condition, usually due to genetic aberrations, that is characterized by a lack of hair growth on the head and/or body. "Here we report the identification of a FOXN1 loss-of-function recessive allele in the Birman feline breed, associated with a syndrome combining hypotrichosis and short life expectancy." (PMID 25781316, 2015).
ichthyosis (1 paper, 2014). Disorders of cornification that are characterized by visible scaling and/or hyperkeratosis of most or all of the skin. "Although the K5CreERT-mediated FoxN1 overexpression mice had a normal lifespan, induction of K5CreERT activation in juveniles adversely influenced total thymoycte development and produced ichthyosis-like skin." (PMID 25299782, 2014). "However, K5CreERT-mediated FoxN1 overexpression via TM induction in the adults resulted in normal thymus and skin, whereas mice subjected to TM induction as neonates had mildly abnormal development of the thymus, and severe ichthyosis-like skin in the juvenile mice." (PMID 25299782, 2014).
influenza infection (1 paper, 2012). "In the current report, we compared the effects of K14-driven FoxN1 deletion on peripheral T cell function with those associated with normal aging, focusing on a physiologically relevant model of influenza infection." (PMID 22514652, 2012). "Hence, we used influenza infection as a model to determine if progressive loss of FoxN1 mimicked the antigen-specific T- and B-cell responses of aging." (PMID 22514652, 2012). "The current report demonstrates that FoxN1 K14KO mice also have fewer naïve T-cells and reduced CD8+ T-cell responses to influenza infection, with increased lung injury, weight loss and mortality." (PMID 22514652, 2012). "This suggests that FoxN1 K14KO mice have a reduced humoral response to influenza infection, similar to findings in aged WT mice." (PMID 22514652, 2012). "The antibody response to influenza vaccination is reduced in the elderly, and we found lower H1-specific IgG levels in aged WT and young FoxN1 K14KO mice." (PMID 22514652, 2012). "Because CD8+ T cells play a dominant role in clearing influenza virus, these results are consistent with a significant defect in the response to influenza in aged mice, which is replicated in the FoxN1 K14KO mice." (PMID 22514652, 2012). "The diminished CD8+ T-cell and B-cell responses to influenza in FoxN1 K14KO mice were biologically relevant and consistent with results from aged mice." (PMID 22514652, 2012). "By 30 days after influenza infection, some aged mice died, so results are only presented for young control and FoxN1 K14KO mice." (PMID 22514652, 2012). "In summary, we found that deletion of FoxN1 in K14-expressing thymic medullary epithelial cells reduces the number of naïve T-cells, decreases the antigen-specific CD8+ T-cell and B-cell response during influenza infection, and increases lung injury, weight loss and mortality." (PMID 22514652, 2012). "The numbers of influenza-specific CD8+ T cells in the lung and spleen were reduced by approximately 50% in young FoxN1 K14KO and aged WT mice, compared to young WT mice (p<0.05)." (PMID 22514652, 2012). "Unlike the case for H1 IgG, IgA levels in the lung homogenates of FoxN1 K14KO mice and young WT mice were not significantly different, 4 and 10 days after influenza infection (data not shown)." (PMID 22514652, 2012).
liver fibrosis (1 paper, 2016). "Herein, we show that using progressive oral administration of low-dose TAA, liver fibrosis can be safely induced in Foxn1 nu/nu mice." (PMID 27792745, 2016). "In conclusion, the induction of liver fibrosis in Foxn1 nu/nu mice by the addition of TAA in drinking water, in a step-wise dose increase, is a reproducible model of liver fibrosis in immunodeficient animals." (PMID 27792745, 2016). "In conclusion, liver fibrosis can be induced in athymic Foxn1 nu/nu mice without early mortality." (PMID 27792745, 2016). "Therefore, a mouse model of liver fibrosis lacking T cells was developed using Foxn1 nu/nu mice and progressive oral administration of thioacetamide (TAA) [0.01–0.02%] in drinking water." (PMID 27792745, 2016). "Therefore, models based on Foxn1 nu/nu mice can be useful for the study of liver fibrosis and T cells are not involved in the hepatocellular protection afforded by liver fibrosis." (PMID 27792745, 2016).
lymphoma (1 paper, 2021). A malignant (clonal) proliferation of B- lymphocytes or T- lymphocytes which involves the lymph nodes, bone marrow and/or extranodal sites. "In this study, 3 patients, carrying homozygous, compound heterozygous, or heterozygous mutations developed EBV-related lymphomas, suggesting that T cell lymphopenia in FOXN1-deficient patients impairs the immunological control of EBV infection." (PMID 33464451, 2021).
mastitis (1 paper, 2020). Inflammation of breast tissue during lactation or postpartum due to an obstructed duct or infection. "Comparison with indigenous pigs showed genes that were associated with mastitis resistance (ARHGAP39, ARPC4, PHC2, and BCL2L15) and hair follicle development (FOXN1)." (PMID 32457791, 2020).
mesothelioma (1 paper, 2020). A usually malignant and aggressive neoplasm of the mesothelium which is often associated with exposure to asbestos. "Control uninfected BALB/cAnNRj-Foxn1 nu/nu mice died much faster from mesothelioma than normal BALB/c animals, which indicates an important role of T lymphocytes in protection against this tumor." (PMID 32391074, 2020). "Because NK cells have been shown to provide help in systemic anti-mesothelioma responses, a possible involvement of T lymphocytes in the protective effect of LDV infection was tested in BALB/cAnNRj-Foxn1 nu/nu mice that are deprived of T cells." (PMID 32391074, 2020).
metastatic tumors (1 paper, 2024). "Secondly, the correlation analysis showed that the expression of FOXN1 was statistically higher in distant metastatic tumors, lymph node-positive tumors, grading G3 and stage IV LUSC patients." (PMID 39628682, 2024).
parasitic infection (1 paper, 2023). "ICR/CD-1 mice are a Foxn1 gene knockout mouse model: this mouse is athymic and T-cell deficient, which makes the mouse immunodeficient and easily susceptible to parasitic infection." (PMID 36830543, 2023).
schizophrenia (1 paper, 2024). A major psychotic disorder characterized by abnormalities in the perception or expression of reality. "Variants in FOXN1 and FLOT2 would have been categorized as damaging from recent schizophrenia and bipolar exome sequencing studies." (PMID 39080272, 2024).
seborrheic keratosis (1 paper, 2017). A common benign skin neoplasm usually affecting older individuals. "All the seborrheic keratosis lesions were also sequenced for the coding regions of FOXN1 and did not carry mutations." (PMID 28410231, 2017). "Seborrheic keratosis, despite being hyper-proliferative remain well differentiated and rather than senescence due to oncogenic signals, a positive feedback loop between FGFR3 and the transcription factor FOXN1 has been suggested to prevent malignant progression of those lesions." (PMID 28410231, 2017).
skin tumors (1 paper, 2022). "Similar to patient samples, nuclear enrichment of YAP was mainly observed in the marginal region of footpad tumors in both C57BL/6J and Foxn1-null mice, whereas YAP was detected primarily in the cytoplasm in the footpad tumor center and flank skin tumors." (PMID 35468978, 2022).
thymus (1 paper, 2021). "In the Δ505 FOXN1 mouse model, this time point corresponds to the first days after birth and is consistent with thymus hypoplasia being observed in these animals only after birth." (PMID 34860543, 2021).
tumor (29 papers, 2014 to 2026). "The nude rat was derived from the Foxn1 gene mutation in Wistar rats in 1953 and is widely used in the study of immunity and tumor biology." (PMID 34884605, 2021). "Some such models are nude mice with Foxn1 gene mutations; these mice lack thymic cell immunity and are used for tumor modeling and for evaluating drug effects." (PMID 28787439, 2017). "In the present study, we used nude mice (BALB/c FOXN1-/-) to explore the effect of Sirt6 on tumor growth and immune surveillance." (PMID 41530841, 2026). "As with OVCA420 cells, ZNF217 overexpression in TYK-Nu cells also resulted in increased metastasis and tumor burden in Foxn1 nude mice." (PMID 41345234, 2025). "Overexpression of FOXN1 inhibited cell proliferation and invasion, while its reduced expression promoted tumor growth." (PMID 39628682, 2024). "In this study, 38 (47.5% of 80) LUSC cases displayed compositive IHC-intensity, revealing the expression of FOXN1 demonstrated a pronounced tendency towards frequent heterogeneity within the tumor samples." (PMID 39628682, 2024). "No other clinicopathological characteristic of LUSC patients, such as age, gender, tumor site, or smoking status, correlated with FOXN1 expression." (PMID 39628682, 2024). "The maximum expression of FOXN1 IHC 3+ was observed in 3 cases with 50.0% proportion of tumor cells." (PMID 39628682, 2024). "For the in vivo anti-tumor activity of Amiodarone, U-87 MG cells were evaluated in S.C. injected Foxn1 nu mice." (PMID 33093573, 2020). "Our Hds:Athymic Nude-Foxn1 animal model characterized by partial defects in B cell development shows tumor-infiltrating CD45 + mouse leukocyte cells in the tumor." (PMID 33033246, 2020). "Consistent with the in vitro results, we observed significantly reduced tumor growth and tumor formation in the knockdown cells compared to shRNA control or the parent MDA-MB-468 cells in female athymic Nude-Foxn1 mice." (PMID 31624295, 2019). "Transplantation of S462 cells resulted in complete tumor development in all Foxn1 mice (4/4), and all tumors reached volumes > 70 mm3 48 days after transplantation." (PMID 30055648, 2018). "Both cell lines successfully formed tumours in nu/nu Foxn1 mice, although the MUG-Myx2a cell line again showed higher proliferation capacity and thereby confirmed the growth analysis data." (PMID 28304377, 2017). "For MDA-MB-231 xenografts, when the tumor volume reached around 500 mm3, four female athymic nude-Foxn1 mice received sunitinib given by gavage at 80 mg/kg/2 days for 4 weeks and the other 4 mice received the vehicle only as the control group." (PMID 24914410, 2014). "For example, FOXN1's role in immune regulation raises the possibility that its expression may enhance the tumor's immunogenicity, making patients more responsive to immune checkpoint inhibitors, which have become a key therapy for LUSC." (PMID 39628682, 2024). "Besides, the significant correlation between FOXN1 expression and key clinical factors, including tumor grade, lymph node involvement, metastasis, and survival outcomes, underscores its potential as a prognostic indicator." (PMID 39628682, 2024). "The Crl: NU(NCr)-Foxn1 nude mice were sacrificed at the end of the study, and H&E staining of tumor tissue, spleen, and intestine was performed according to the standard protocol described in the “Histological studies of HK-1 nasopharyngeal HNSCC xenograft model” section." (PMID 36230831, 2022). "As in Foxn1 mice, in an NSG i.p injection model using OVCA420 cells, ZNF217 overexpression resulted in increased metastasis, higher tumor burden, and decreased survival." (PMID 41345234, 2025). "Consistent with ZNF217’s ability to drive aggressive metastatic tumor formation, i.p injection of ZNF217 overexpressing cells resulted in a striking decrease in survival in Foxn1 nude mice." (PMID 41345234, 2025). "Initially, no significant statistical difference in FOXN1 expression was observed between the various tumor stages." (PMID 39628682, 2024).
tumor (continued). "Besides, a robust correlation was found between FOXN1 expression and various clinical features of LUSC, such as tumor grading, lymph node involvement, distant metastasis, disease stage, and patient survival." (PMID 39628682, 2024). "When the tumor volume reached around 100 mm3 in the basal-like TNBC (MDA-MB-468) xenografts, four female athymic nude-Foxn1 mice received sunitinib given by gavage at 80 mg/kg/2 days for 4 weeks and the other 4 mice received the vehicle only as the control group." (PMID 24914410, 2014). "Notably, the forkhead transcription factor FOXN1, essential for normal cutaneous and thymic epithelial development, and OVOL1, a critical regulator of epithelial lineage determination and differentiation, were downregulated upon tumor occurrence." (PMID 40678065, 2025). "To directly assess this hypothesis, we performed the same endurance training program and tumor growth study with 4 T1 cells on immunodeficient athymic BALB/c mice that do not have mature T cells (Foxn1−/− nude BALB/c, Charles River Labs)." (PMID 31164094, 2019). "Transplants of T265 cells did not generate tumors in Foxn1 mice whereas SHO and Shorn mice developed one flank tumor each (2 tumors/4 transplants) with only 1 tumor gaining a volume > 70 mm3." (PMID 30055648, 2018).
cancer (12 papers, 2008 to 2024). A tumor composed of atypical neoplastic, often pleomorphic cells that invade other tissues. "This is remarkable, since CSQCC and TETs are the only cancers that commonly express the thymus-‘specific’ transcriptional master regulator and survival factor, FOXN1." (PMID 29163772, 2017). "The FoxN1 gene and protein are also directly or indirectly important in many other developmental processes, immune system regulation, metabolism, cancer and aging." (PMID 26933816, 2016). "Thirdly, we found that FOXN1 expression is correlated with cancer survival of LUSC patients meaningfully, so it may be used as a potential prognostic biomarker for LUSC." (PMID 39628682, 2024). "The forkhead box N1 (FOXN1) gene belongs to the forkhead box gene family that comprises a diverse group of “winged-helix” transcription factors implicated in various biochemicals and cellular processes as development, metabolism, aging, and cancer." (PMID 34113558, 2021). "Athymic nude mice with a deletion of Foxn1 have been widely used in cancer research." (PMID 28798321, 2017). "Athymic nude mice, which are widely used as models in cancer research, bear spontaneous FOXN1 deletion and have dysfunctional or absent thymus, resulting in an impaired immune system with downregulation of T cells." (PMID 38967635, 2024).
infection (5 papers, 2012 to 2025). The state of being infected such as from the introduction of a foreign agent such as serum, vaccine, antigenic substance or organism. "The other two patients had cartilage-hair hypoplasia syndrome and FOXN1 deficiency and they were unable to generate any IgG or cellular response after infection or a combination of vaccination and infection." (PMID 41280926, 2025). "H1-specific IgG levels in aged mice were markedly reduced at 10 days after infection, and H1 IgG levels were significantly lower in young FoxN1 K14KO mice, although they were higher than those in aged mice." (PMID 22514652, 2012). "However, LDV infection still delayed death of these BALB/cAnNRj-Foxn1 nu/nu animals by approximately ten days (p = 0.0008)." (PMID 32391074, 2020). "Ten days after infection with PR8 virus, mean lung volumes at peak inspiration were 0.35±0.06, 0.19±0.05, and 0.23±0.05 mm3 in young control, FoxN1 K14KO and aged mice, respectively." (PMID 22514652, 2012). "FoxN1 K14KO mice had significantly higher titers than young control mice, 4 and 10 days post-infection." (PMID 22514652, 2012). "At this time point, H1 IgG levels were markedly reduced in FoxN1 K14KO mice, to a greater degree than at 10 days after infection." (PMID 22514652, 2012). "To evaluate the antibody response in FoxN1 K14KO mice, we measured IgG to the H1 component of influenza A in the sera of PR8-infected mice, 10 and 30 days after infection." (PMID 22514652, 2012).
hematological cancers (1 paper, 2017). "The elevation of TEI scores caused by Foxn1 deletion was more significant for subcutaneous solid tumors than for hematological cancers." (PMID 28798321, 2017).
FOXN1 also shares sentences with these, for which no sentence is quoted: combined immunodeficiency (4 papers); Alopecia universalis (3); coloboma (3); endometrial cancer (2); Otofaciocervical Syndrome type 2 (2); retinal degeneration (2); spina bifida (2); age (1); anencephaly (1); ataxia telangiectasia (1); autism spectrum disorder (1); autoimmune disorders (1); B cell deficiency (1); B-cell acute lymphoblastic leukemia (1); Bamforth-Lazarus syndrome (1); bladder cancer (1); Blepharophimosis (1); Burkitt lymphoma (1); chronic kidney disease (1); coronary aneurysm (1); developmental delay (1); endometriosis (1); Epicanthus inversus (1); fibrosarcoma (1); genetic disorders (1); Hematological Disease (1); hereditary spherocytosis (1); Hydrocephalus (1); inflammation (1); injury (1).
A further 16 diseases each share a sentence with FOXN1 in 1 paper.